ALK (ALK receptor tyrosine kinase)
Diseases named in the same sentence as ALK in open-access papers (continued):
Sharing a sentence is not in itself a finding about the gene and the disease.
pancreatic cancer (36 papers, 2013 to 2025). "Still, the most pronounced responses were observed either in patients with already approved organ-specific drug indications (e.g., olaparib in BRCA1/2-driven pancreatic cancer), or in subjects with overtly actionable lesions (ALK fusions, BRAF V600E mutations, microsatellite instability, etc.)." (PMID 38612902, 2024). "Although our results align with this finding, the understanding of ALK’s role in pancreatic cancer prognosis remains constrained due to limited data." (PMID 39123462, 2024). "Since ALK gene fusion was first identified in pancreatic cancer in 2017, so far, only sporadic ALK translocation cases have been reported in PDAC." (PMID 34671564, 2021). "When applied to a large collection of published pancreatic cancer samples (n = 803), Arriba identified a variety of driver fusions, many of which affected druggable proteins, including ALK, BRAF, FGFR2, NRG1, NTRK1, NTRK3, RET, and ROS1." (PMID 33441414, 2021). "Crizotinib, a c-MET/ALK inhibitor, shows antitumor activity in pancreatic cancer cells via suppressing growth and inducing apoptosis." (PMID 30360560, 2018). "Further, in pancreatic cancer cell lines used in this study, high expression of ALK was observed (AsPC-1, MIA PaCa-2, PANC-1)." (PMID 25193856, 2014). "Taken together, our investigation shows that Crizotinib inhibits the ALK signaling pathway in pancreatic cancer, resulting in cell growth/angiogenesis inhibition and apoptosis induction." (PMID 25193856, 2014). "From our results, Crizotinib inhibited the expression of p-ALK in PANC-1 pancreatic cancer cells, in a dose dependent manner." (PMID 25193856, 2014). "In 42 different receptor tyrosine kinase (RTKs) array, Crizotinib also strongly inhibited the expression of activated ALK in pancreatic cancer cells, modulating its downstream mediators such as STAT3, AKT, and ERK." (PMID 25193856, 2014). "Some of these fusions, like Echinoderm Microtubule-Associated Protein-Like 4 (EML4)-ALK and Striatin (STRN)-ALK, may be found in pancreatic tumors." (PMID 41374970, 2025). "ALK rearrangements are extremely rare in GI cancers, with a frequency of <1% in colorectal cancer, 0.2% in pancreatic cancer, and 0.9% to 2.3% in gastric cancer, but may offer personalized treatment strategies in selected patients." (PMID 41246301, 2025). "To test this hypothesis, we evaluated tumor and serum miR expression immediately after short-term treatment of pancreatic tumor xenografts with either the FGFR or ALK inhibitor in a COLO357PL model expressing both FGFR and ALK receptors." (PMID 35326668, 2022). "Additionally, it has been shown that blocking ALK signaling by TAE684 exerts anti-tumor effects in pancreatic cancer, while ALK inhibition by crizotinib suppresses pancreatic tumor growth, cell proliferation, and angiogenesis and induces apoptosis." (PMID 35326668, 2022). "ALK rearrangement-positive is rare in pancreatic cancer, but may occur in those with KRAS-wild type." (PMID 34568053, 2021). "Furthermore, the use of ALK inhibitors in pancreatic cancer patients is currently under investigation." (PMID 34219130, 2021). "In contrast, we identified two RTKs, EPHA10 and ALK, which are associated with a good prognosis in patients with pancreatic cancer regardless of the immune status." (PMID 34479614, 2021). "Therefore, we used tissue array to analyze the expression of p-ALK in human pancreatic tumor tissue." (PMID 25193856, 2014). "In the study, with regard to the mechanism of action, Crizotinib did not inhibit c-MET expression on pancreatic cancer cells; instead, it specifically inhibited the activity of ALK, which was identified to be highly expressed on various pancreatic cancer cells and tissues in our study." (PMID 25193856, 2014). "Our discovery of this novel anticancer mechanism of Crizotinib may be useful for a novel drug targeting ALK in pancreatic cancer." (PMID 25193856, 2014).
pancreatic cancer (continued). "The expression of phosphorylated ALK was higher in pancreatic tumors than in the normal pancreas." (PMID 25193856, 2014). "Therefore, we investigated the effect of Crizotinib on the expression of p-ALK in pancreatic cancer." (PMID 25193856, 2014). "In addition, to observe the expression of ALK in pancreatic cancer patients, we performed a human tissue array." (PMID 25193856, 2014). "Furthermore, p-ALK was significantly expressed in pancreatic cancer cell lines (AsPC-1, MIA PaCa-2, PANC-1) we used." (PMID 25193856, 2014). "Surprisingly, ALK was highly expressed in pancreatic cancer cells than normal pancreas tissues." (PMID 25193856, 2014). "However, studies regarding ALK expression in pancreatic cancer was limited." (PMID 25193856, 2014). "Terms involved in cancer also appeared as enriched, including “MicroRNAs in cancer” (log (q) = −2.05), “Signaling by ALK in cancer” (log (q) = −2.04), and “NRP1 triggered signaling pathways in pancreatic cancer” (log (q) = −1.57)." (PMID 40282383, 2025). "We present a 34-year-old young man with ALK rearrangement-positive and KRAS-wild pancreatic cancer who had a remarkable response to crizotinib after resistance to prior chemotherapy and re-response to alectinib after brain metastases developed." (PMID 34568053, 2021). "Recent efforts have identified multiple dysregulated signaling pathways in pancreatic cancer development and progression, many of which appear to be reasonable targets including PI3K/mTOR, SIRT1, and ALK." (PMID 26369833, 2015). "Mice with pancreatic cancer cell (COLO357PL) xenografts were treated with inhibitors of either fibroblast growth factor receptor kinase (FGFR; PD173074) or anaplastic lymphoma kinase receptor (ALK; TAE684)." (PMID 35326668, 2022). "A recent study demonstrated Crizotinib exhibits anti-tumor activity by targeting ALK but not c-MET in pancreatic cancer." (PMID 25909285, 2015). "Although relevance between the expression of ALK and ALK gene alteration in pancreatic cancer remains to be further investigated, Crizotinib obviously showed an anticancer effect via target inhibition of ALK, and not c-MET." (PMID 25193856, 2014). "Interestingly, we found that among the 42 RTKs, Crizotinib inhibited the phosphorylation of ALK more than other tyrosine kinase receptors in both PANC-1 and MIA PaCa-2 pancreatic cancer cells." (PMID 25193856, 2014). "In conclusion, we demonstrate that Crizotinib suppresses tumor growth and angiogenesis and induces apoptosis by downregulating the ALK signaling pathway, and not c-MET in pancreatic cancer." (PMID 25193856, 2014). "Our present study revealed that Crizotinib induced apoptosis and inhibited cell growth or angiogenesis via inhibition of ALK signaling, not c-MET signaling in pancreatic cancer." (PMID 25193856, 2014). "For the first time, we report that Crizotinib inhibited ALK signaling pathway and not c-MET, which may lead to the induction of apoptosis along with the inhibition of cell growth and angiogenesis in pancreatic cancer." (PMID 25193856, 2014).
B-cell lymphoma (34 papers, 2006 to 2026). "We focused here for the first time on allelic imbalance of tumours with ALK fusion with a novel technique which has already shown the involvement of loss of A20 function in the pathogenesis of a subset of B-cell lymphomas and gain of function of C-CBL tumour suppressor in myeloid neoplasms." (PMID 23289484, 2013). "Anaplastic lymphoma kinase-positive large B-cell lymphoma (ALK+-LBCL) is an aggressive and rare B-cell lymphoma caused by the ALK gene mutation." (PMID 41798535, 2026). "Distinguishing plasmablastic lymphoma (PBL) from ALK-positive large B-cell lymphoma (ALK+ LBCL) is vital due to their overlapping morphologic and immunophenotypic features, yet different clinical behaviors and therapeutic implications." (PMID 40428800, 2025). "Protein analysis showed an increase in the high glycosylation form (HG-CD147) in ALK+ anaplastic large-cell lymphoma (ALCL) cell lines, ALK− cell lines, and several B-cell lymphoma cell lines." (PMID 39273126, 2024). "Anaplastic lymphoma kinase-positive large B-cell lymphoma (ALK+ LBCL) is a rare invasive B-cell lymphoma that has plasmablast/immunoblast morphology and ALK fusion protein expression." (PMID 39906668, 2024). "ALK-positive large B cell lymphoma is a rare tumour with characteristic pathological and clinical feature." (PMID 28665943, 2017). "Gain-of-function ALK gene alterations have been detected in several types of solid tumors, B cell lymphomas and pediatric tumors, for which crizotinib has either established or promising clinical efficacy." (PMID 26966027, 2016). "ALK+ DLBCL is a rare and aggressive form of B-cell lymphoma exhibiting plasmablastic differentiation, which was initially described in 1997 by Delson and colleagues as an immunoblastic or plasmablastic large cell lymphoma with constant ALK immunohistochemical expression." (PMID 34283060, 2021). "Anaplastic lymphoma kinase (ALK) positive large B-cell lymphoma (ALK+ LBCL) is an aggressive and rare subtype of B-cell lymphoma." (PMID 37305584, 2023). "ALK+ LBCL is a rare, aggressive B-cell lymphoma with characteristic morphologic, immunophenotypic and cytogenetic/molecular findings." (PMID 22474449, 2012). "However, rare cases of mature B cell lymphoma not expressing any B cell markers have been characterized and recognized as distinct diagnostic entities by current classification guidelines, including plasmablastic lymphoma, primary effusion lymphoma, and ALK-positive large B cell lymphoma." (PMID 39055348, 2024). "Therefore, differentiation diagnosis must also be conducted between ALK+ ALCL and other subtypes of T-cell or B-cell lymphomas that display anaplastic features or CD30 expression." (PMID 37443818, 2023). "Therefore, ALK− ALCL should be distinguished from conditions like primary cutaneous ALCL (C-ALCL), various subtypes of CD30+ T-cell or B-cell lymphoma subtypes exhibiting anaplastic features, or classic Hodgkin lymphoma (CHL)." (PMID 37443818, 2023). "In addition, STING mRNA levels were very high in 6 out of 7 T-cell NHL cell lines, namely, ALK+ and ALK-ALCL cell lines, and very low or undetectable in 7 B-cell NHL cell lines, suggesting transcriptional downregulation of STING in neoplastic B-cells." (PMID 35267494, 2022). "In fact, neoplastic MC did not express any of the T cell- or B cell-restricted antigens analyzed (except ALK), and the T cell- and B cell-lymphomas did not express MC antigens such as KIT, tryptase, or chymase." (PMID 21297223, 2010). "Pan-B cell marker negative B cell lymphomas are rare, most commonly observed in ALK positive large B cell lymphoma (ALK + LBCL), plasmablastic lymphoma (PBL), primary effusion lymphoma (PEL), HHV8+ large B cell lymphoma (HHV8+ LBCL), and unclassifiable large B cell lymphoma." (PMID 39055348, 2024). "As there is no standardized treatment for ALK+ LBCL, most patients are treated using B-cell lymphoma regimens." (PMID 39906668, 2024).
B-cell lymphoma (continued). "Only 12 cases (2.8%) were true new entities, including seven cases of high-grade B-cell lymphoma NOS, three of anaplastic large B-cell lymphoma, ALK-negative, 1 case of HHV8+ DLBCL NOS, and 1 of high-grade B-cell lymphoma with C-MYC and BCL2/BCL6 rearrangement." (PMID 35932211, 2022).
lymph node metastasis (33 papers, 2014 to 2025). "Several studies suggest ALK mutations are linked to lymph node metastasis, indicating poor prognosis." (PMID 41378298, 2025). "In this study, we found that ALK mutation is associated with pathological features of tumors (lymph node metastasis, TNM stage, differentiation) as well as mortality." (PMID 36401689, 2022). "The risk of lymph node metastasis in ALK positive patients was significantly lower than that in negative patients." (PMID 36401689, 2022). "Serum LAPTM4B levels of LAC patients were significantly correlated with smoking, advanced clinical stages, lymph node metastasis, anaplastic lymphoma kinase (ALK) rearrangements and EGFR mutations." (PMID 30940109, 2019). "Moreover, ALK rearranged patients had a higher risk of lymph node metastasis and more advanced stage, which had also been confirmed in other studies." (PMID 34596344, 2021). "Furthermore, serum LAPTM4B levels were positively correlated with smoking, advanced clinical stages, lymph node metastasis, ALK rearrangements and EGFR mutations." (PMID 30940109, 2019). "Additionally, there are no obvious differences of positive ratio among gender, age, clinical stage, lymph node metastasis, distant metastasis, ALK mutation status, EGFR mutation status and PDL1 expression (P>0.05) except diameter between high UBQNL1 expression and low UBQNL1 expression." (PMID 38431566, 2024). "LC_08PE patient was diagnosed as a tumor with MPE and lymph node metastasis and was resistant to the ALK-targeted drug alectinib, despite being positive for EGFR exon 19 deletion and ALK rearrangement." (PMID 37993887, 2023). "Multivariate Cox regression analysis showed that Beclin 1, EGFR, ALK mutations, tumor differentiation grade, TNM stage and lymph node metastasis were independently associated with PFS." (PMID 36401689, 2022). "In multivariate analysis, lymph node metastasis, EGFR-mutations, and ALK were independent predictors of NSCLC." (PMID 35644823, 2022). "Patients with ALK+ were more likely to have lymph node metastasis compared to ALK- patients (p = 0.002)." (PMID 24422905, 2014). "In this study, the ALK+ patients were significantly younger and more likely to have lymph node metastasis compared to ALK- patients." (PMID 24422905, 2014). "Univariate analysis showed that Beclin 1 expression and EGFR and ALK mutations were associated with lymph node metastasis, TNM stage, tumor differentiation and prognosis, but not with gender, age and smoking status (P < 0.05)." (PMID 36401689, 2022). "Univariate analysis revealed that Beclin 1 level, EGFR and ALK mutations were associated with lymph node metastasis, TNM stage, tumor differentiation and prognosis, but not with gender, age and smoking status." (PMID 36401689, 2022). "In addition, our previous report revealed a significantly higher incidence of occult lymph node metastases in ALK-positive NSCLC, which makes these patients good candidates for adjuvant chemotherapy according to the clinical guidelines." (PMID 34064047, 2021). "Specifically, the risk of lymph node metastasis in ALK‐positive patients is greater than in ALK‐negative patients (28.8% vs. 18.3%; p = 0.028)." (PMID 34596344, 2021). "In the group of patients receiving second-generation ALKis, the risk of death was independent of sex, age, body weight, smoking status, ALK gene abnormality diagnostic method, primary tumor size and location, lymph node metastasis, CNS and bone metastasis, and treatment complications." (PMID 40227844, 2025). "Given the ALK-negative results, the effect of alectinib on the right axillary lymph node metastases was expected to be limited." (PMID 39781173, 2024).
lymph node metastasis (continued). "The expression of USP5 was not related to gender, age, lymph node metastasis, pathological grade, the EGFR mutation and ALK translocation but was related to tumor size, and the difference was statistically significant." (PMID 36611139, 2023). "Because the somatic EML4-ALK v3 rearrangement was affirmatively identified in newly acquired biopsy material from a lymph node metastasis using whole genome sequencing, the patient was considered a potential candidate for inclusion in the DRUP trial with ALK as a therapeutic target." (PMID 33878728, 2021). "The primary, recurrence, and lymph node metastasis lesions were diagnosed as ALK-negative IMTs based on the histopathological features." (PMID 32195970, 2020). "In this group, the risk of death was not significantly related to age, gender, ALK abnormality testing method (IHC vs. FISH vs. NGS), body weight, smoking status, location of lymph node metastases, size and location of tumor, nor to bone metastases and secondary CNS metastases." (PMID 40227844, 2025). "The current case was negative for ALK and lymph node metastasis was present." (PMID 26445324, 2015).
leukemia (31 papers, 2011 to 2025). A malignant (clonal) hematologic disorder, involving hematopoietic stem cells and characterized by the presence of primitive or atypical myeloid or lymphoid cells in the bone marrow and the blood. "This alteration has been reported to confer resistance to CRIZOTINIB and second generation ALK inhibitors, leading to resistance through phosphorylation or other activation signaling pathways described in leukemia." (PMID 39931211, 2024). "Thus, ALK inhibition alone hardly explains the remarkably high sensitivity of our leukemia and multiple myeloma cell lines to crizotinib." (PMID 34832908, 2021). "Some pluripotency genes were also identified, as well as cancer genes, such as TET1, ALK, EP300, ERG, MKL1 and PHF6, already described as being involved in leukemia." (PMID 37174060, 2023). "ALK fusions are also found in DLBCL but also in differentiated B cell lymphomas, some leukemias, myelomas and histiocytosis." (PMID 37773318, 2023).